IGF2BP2 (insulin like growth factor 2 mRNA binding protein 2)
Diseases named in the same sentence as IGF2BP2 in open-access papers (continued):
Sharing a sentence is not in itself a finding about the gene and the disease.
tumor (continued). "Finally, in a cohort of 38 HNSCC patient tumour samples, over-expression of Lin28b, IGF2BP2, and IGF2 were observed to be associated with worse clinical outcome, strongly suggesting a role for the Lin28b-IGF pathway in contributing to HNSCC relapse." (PMID 23482325, 2012). "Interestingly, stratifying by tumour stage revealed a stepwise increase in the levels of lactylation, H3K18la, IGF2BP2 and Nrf2 with increasing tumour burden, suggesting a strong association between the lactate–IGF2BP2–Nrf2 axis and disease progression." (PMID 41399129, 2025). "Furthermore, elevated IGF2BP2 expression in primary tumor tissue was significantly linked to resistance against multiple therapies, including selumetinib, gefitinib, and regorafenib in patient-derived organoids (PDOs), as well as 5-fluorouracil and oxaliplatin." (PMID 39596216, 2024). "Similarly, another study showed that IGF2BP2 was correlated with clinical outcome and multiple biological processes involved in cancer, of which the most significant processes were associated with cancer cell cycle, immortalization, and tumor immunity." (PMID 34239358, 2021). "In GC, RBM15 regulates ACLY mRNA in an IGF2BP2-dependent manner, thereby increasing its expression and enhancing tumor cell adipogenesis." (PMID 41522342, 2026). "Here, we reveal a critical function of IGF2BP2 in macrophages, demonstrating that myeloid-specific deletion of IGF2BP2 profoundly alters macrophage metabolism and polarization, and markedly impairs tumor progression." (PMID 41943844, 2026). "Tunel staining showed that inhibition of circGDI2 promoted tumor cell apoptosis, which was reversed by overexpression of IGF2BP2." (PMID 41439029, 2026). "Silencing FTO inhibited HCC cell proliferation, glycolysis, and tumor growth, and decreased the levels of circGDI2, IGF2BP2, and PKM2." (PMID 41439029, 2026). "CircGDI2 knockdown led to disrupted tumor tissue, and overexpressing IGF2BP2 partially reversed these effects." (PMID 41439029, 2026). "Insulin-like growth factor 2 mRNA binding protein 2 (IGF2BP2) targets distinct types of RNA species to orchestrate tumor cell metabolism, invasion, and metastasis." (PMID 42158820, 2026). "The results elucidated that silencing circGDI2 significantly suppressed the tumor weight and volume, and overexpressing IGF2BP2 partially reversed the inhibitory influence of circGDI2 knockdown." (PMID 41439029, 2026). "Further expression analysis of COAD samples using the GEPIA2 database demonstrated that among these candidates, only IGF2BP2 was significantly up‐regulated in tumour tissues." (PMID 41399129, 2025). "Targeting IGF2BP2 effectively overcomes anti-EGFR-resistance mediated by either intracellular PI3K/AKT signaling hyperactivation or CAF-mediated tumor microenvironment interactions." (PMID 40362183, 2025). "Results of further analysis revealed a dramatic increase in IGF2BP2 expression in metastatic HNSCC tumor cells compared with primary HNSCC tumor cells." (PMID 40362183, 2025). "We also analysed data from TCGA database and found that IGF2BP2 mRNA expression was significantly higher in COAD tumour tissues." (PMID 41399129, 2025). "Complementing this, m6A “reader” IGF2BP proteins stabilize pro-angiogenic transcripts such as VEGFA and EPHA2, and exosomal transfer of IGF2BP2 from tumor cells can activate endothelial PI3K–AKT signaling to drive vessel formation and metastatic spread." (PMID 41280938, 2025). "In vivo, xenograft assays confirmed that IGF2BP2 knockdown significantly inhibited tumor growth, with CBP further enhancing this effect." (PMID 40270464, 2025). "This is an unrecognized mechanism by which IGF2BP2 inhibits tumour progression in an m6A cooperated with APA manner." (PMID 40629911, 2025). "In these models, we will systematically evaluate the impact of IGF2BP2 expression on tumor progression and glycolytic activity." (PMID 40469197, 2025).
tumor (continued). "This interaction enables IGF2BP2 to promote tumor progression by stabilizing MEKK1 mRNA in an m6A-dependent manner and activating the p-ERK1/2 pathway." (PMID 41041073, 2025). "The pharmacological inhibition of IGF2BP2 suppresses tumor growth, offering a promising therapeutic strategy for PLK1-driven malignancies." (PMID 40347943, 2025). "In vivo, a CDX tumor model was established by injecting IGF2BP2‐overexpressing shPRMT1#1 LIU‐LSC‐1 cells or control cells into nude mice." (PMID 40270464, 2025). "Our findings revealed that lactate up‐regulates IGF2BP2 through H3K18la‐mediated transcriptional activation in both CRC cells and tumour‐associated macrophages." (PMID 41399129, 2025). "Though overall in most cancers analyzed, high expression of IGF2BP2 mRNA was associated with worse overall survival, thereby supporting the oncogenic role of IMP2 across a broad range of tumor types." (PMID 40141058, 2025). "The analysis of leukocyte subsets indicated that the high expression of IGF2BP2 was highly negatively related to the infiltration of tumor-infiltrating lymphocytes (TILs)." (PMID 40746360, 2025). "Immunohistochemistry (IHC) assay of excised tumor sections showed increased expression of IGF2BP2 and Ki67 in tumors of mice treated with hsa_circ_0058495 over-expressed exosomes." (PMID 41041073, 2025). "In the lactate‐rich tumor microenvironment, p300‐mediated H3K18la epigenetically activates IGF2BP2 transcription." (PMID 41399129, 2025). "It recruits the SWI/SNF complex to activate IGF2BP2, promoting tumor growth and carboplatin resistance." (PMID 40270464, 2025). "The scRNA-seq dataset from 22 HNSCC tissues demonstrated that IGF2BP2 had the highest expression abundance in tumor cells and CAFs compared with other four RBPs or other cell types." (PMID 40362183, 2025). "Conversely, pharmacological inhibition of ferroptosis resistance with dichloroacetate (DCA) or depletion of IGF2BP2 significantly reduced tumour burden." (PMID 41399129, 2025). "Co-expression of IGF2BP2 in patients with pancreatic cancer exacerbates tumor proliferation and migration, thereby hastening disease progression." (PMID 39791162, 2025). "IGF2BP2 expression was significantly higher in patients with tumor diameters larger than 5 cm, whereas it was lower in those with tumors smaller than 5 cm." (PMID 40469197, 2025). "To investigate the relationship between METTL3 or IGF2BP2 and radiosensitivity in vivo, we established a mouse xenograft model and irradiated the primary tumor site using irradiator." (PMID 39799112, 2025). "Accordingly, this pathway is likely to promote M2 macrophage polarization within the tumor microenvironment—pointing to IGF2BP2 inhibition as a promising strategy to restore DPP sensitivity in SCLC." (PMID 41157107, 2025). "A pan-cancer analysis of IGF2BP2 mRNA expression derived from GEPIA2 revealed significantly increased expression in 13 tumor types relative to normal tissues and decreased expression in three tumor types." (PMID 40141058, 2025). "Compared with those in the sh‐NC group, the percentage of Ki‐67‐positive tumor tissues in the sh‐IGF2BP2 group was lower (p < 0.05), and the expression levels of IGF2BP2, circRNF20, and CDCA4 were lower (p < 0.05)." (PMID 39969065, 2025). "In vivo experiments involving the subcutaneous implantation of sh-Control, sh-NAT10, and sh-IGF2BP2 CAL27 cells in nude mice demonstrated a significant decrease in tumor size with the interference of NAT10 and IGF2BP2 (p < 0.001)." (PMID 40597017, 2025). "Western blotting revealed significant upregulation of PUM2, METTL3, and IGF2BP2 in tumour tissues compared with normal controls." (PMID 40629911, 2025). "The stability of circRNF20 was tested after treatment with actinomycin D. A nude mouse xenograft tumor model was established to validate the effect of IGF2BP2 in vivo." (PMID 39969065, 2025).
tumor (continued). "Next, we analyzed IGF2BP2 expression in 168 tumor samples from CRPC patients available in cBioPortal (PRAD_SU2C_2019 study), classified based on their Gleason scores." (PMID 39948708, 2025). "Among the top 100 deregulated genes, Wnt-associated genes such as LGR5, DKK1, and NKD1, as well as the HB-related genes DUSP9, DLK1, PEG3, PEG10, IGF2BP1, and IGF2BP2 were consistently upregulated in tumor samples." (PMID 40968384, 2025). "Clinical data analysis revealed a strong correlation between high levels of PBX2, PRMT1, SMARCC1, and IGF2BP2 with poor prognosis and tumor progression in HNSCC patients." (PMID 40270464, 2025). "Overexpression of IGF2BP2 is known to promote tumor progression in a variety of malignancies, such as glioblastoma and colorectal cancer." (PMID 39948708, 2025). "Pan‐cancer analysis similarly indicated that elevated IGF2BP2 expression correlated with shorter survival time and higher tumor grades across a diverse range of cancer types." (PMID 38682020, 2024). "As a predicted target gene of MAFG-DT, IGF2BP2 was highly expressed in tumor tissues in our study, especially in high pathological stages." (PMID 39550498, 2024). "This article discusses the structure and physiological functions of IGF2BP2, highlighting its role in cancer development and progression, as well as its involvement in tumor drug resistance." (PMID 39596216, 2024). "In an in vivo subcutaneous tumor model, knockdown of IGF2BP2 or SLC7A5 inhibited tumor growth and enhanced the antitumor effects of IR, while co-knockdown of IGF2BP2 and SLC7A5 had the strongest anti-tumor effects." (PMID 38281999, 2024). "Metastasis is the deadliest aspect of cancer, and IGF2BP2 has been shown to promote tumor metastasis by regulating processes such as tumor angiogenesis and epithelial–mesenchymal transition (EMT)." (PMID 39596216, 2024). "IGF2BP2 is a promising therapeutic target in cancer treatment due to its extensive role in promoting oncogenic processes such as tumor growth, metastasis, drug resistance, and metabolic reprogramming." (PMID 39596216, 2024). "IGF2BP2 can stabilize tumor RNA through an m6A-dependent mechanism, similar to its role in physiological processes." (PMID 39596216, 2024). "While IGF2BP2 is thought to act as a tumor promoter, the mechanisms that regulate its role in RNA metabolism are not well understood." (PMID 38724996, 2024). "Through RT-qPCR and WB analysis, we confirmed that IGF2BP2 expression was higher in BCa tumor tissues than in normal tissues at the mRNA and protein levels." (PMID 39014364, 2024). "Integrative omics analysis highlights the potent influence of methionine/SAM on NR4A2 expression in a tumor-specific manner, mediated by the IGF2BP2-dependent stabilization of methylated NR4A2 mRNA." (PMID 38570607, 2024). "The tumor tissues stained more strongly with anti-IGF2BP2 antibody than normal adjacent bladder tissues." (PMID 39550498, 2024). "Among the m6A reader proteins, IGF2BP2 has been reported to be closely involved in tumor progression by binding to m6A modification sites to regulate the stability and translation of target mRNAs." (PMID 38782769, 2024). "As a predicted target gene of MAFG-DT, IGF2BP2 was highly expressed in tumour tissues, especially in high pathological stages." (PMID 39768623, 2024). "The data form GENT indicated an upregulation in the expression of METTL3, RRM2B, OPA1 and IGF2BP2 in CRC tumor tissues compared with normal tissues." (PMID 38549713, 2024). "Compared to the Lv-si-NC group, most of m6A-modified genes and m6A abundance of common peaks were markedly decreased in tumor tissues in the Lv-si-IGF2BP2 group." (PMID 39731162, 2024). "CircITGB6 in OC facilitates IGF2BP2-mediated FGF9 expression and polarization of tumor-associated macrophages towards the M2 phenotype, conferring DDP resistance." (PMID 38671354, 2024).
tumor (continued). "Our results unveil a tumor-promotive role of IGF2BP2 in OSCC progression through the induction of EREG expression and cancer cell invasion." (PMID 38250159, 2024). "The biological functions of the FTO/GAS5/IGF2BP2/QKI axis was assessed using the tumor xenograft assay." (PMID 38782769, 2024). "For example, in LC, miR-320b suppresses angiogenesis and tumor growth by downregulating the expression of IGF2BP2 and thymidine kinase 1 (TK1)." (PMID 39295872, 2024). "Another exosomal circASPH enhances the stability of STING mRNA by directly binding to IGF2BP2, thereby increasing the transition of macrophages from M1 to M2 and promoting tumor growth." (PMID 39584047, 2024). "Research has shown that IGF2BP2 is over-expressed in a number of cancers and is a contributor to tumor progression." (PMID 38724996, 2024). "The correlation between IGF2BP2 and p62 expression in patient tumor samples highlights the clinical relevance of our findings." (PMID 38682020, 2024). "In pancreatic cancer, lncPACERR promotes M2-like TAMs polarization via IGF2BP2, thereby driving tumor progression." (PMID 39098905, 2024). "Significantly, DDP treatment caused a significant reduction in Spon2 levels in both A549/DDP cells and tumor tissues from A549/DDP xenograft mice, compared to the A549/DDP group; meanwhile, IGF2BP2 deficiency further reduced Spon2 expression." (PMID 39731162, 2024). "IGF2BP2 has been proposed as a tumor promoter and shown to affect many cancer hallmarks through positive or negative regulation of its target genes." (PMID 38250159, 2024). "IGF2BP2 also regulates ncRNAs and circRNAs, which contribute to tumor initiation and progression, and promotes key metastatic processes like angiogenesis and EMT." (PMID 39596216, 2024). "In 3D cell culture, which better recapitulates in vivo tumor growth, a growth inhibiting effect of IGF2BP2 KO was confirmed." (PMID 37248468, 2023). "From the view of growth curve of tumor size, we apparently found that knockdown IGF2BP2 inhibited tumors growth compared with Ctrls group (P < 0.05)." (PMID 37060505, 2023). "METTL3, FTO, and IGF2BP2 have been shown to function as tumour promoters through the C-myc pathway in an m6A-dependent manner in a range of cancers." (PMID 37444417, 2023). "IGF2BP2 is a critical m6A reader that regulates post-transcriptional gene expression and participates in a variety of tumor behaviors, including tumor growth, metastasis, angiogenesis, aerobic glycolysis, immune microenvironment, and drug resistance." (PMID 38042777, 2023). "According to earlier research, IGF2BP2 is a crucial tumor-promoting factor in the development of CRC20." (PMID 37828232, 2023). "Accumulating evidence suggests that IGF2BP2 is a major contributor to tumor initiation and development." (PMID 37936610, 2023). "Distinguishingly, IGF2BP2 is ubiquitously expressed in normal adult and tumor tissues, whereas IGF2BP1 and IGF2BP3 are de novo synthesized during numerous malignancies, earning themselves the label of bona fide oncofetal proteins." (PMID 37554271, 2023). "We performed morphological examination on the collected tumor samples and found that si-IGF2BP2 inhibited proliferation and promoted apoptosis in tumor tissue." (PMID 37060505, 2023). "The weight of tumors in CSF2 knockdown and IGF2BP2 knockdown groups was approximately half of those in GC-MSCs group, further substantiating the roles of CSF2 and IGF2BP2 in maintaining the tumor-promoting roles of GC-MSCs." (PMID 37865637, 2023). "In xenograft tumor model derived from IGF2BP2 knocked-down LSCC cells, IGF2BP2 knockdown inhibited tumor growth." (PMID 37816718, 2023). "In conclusion, IGF2BP2 promotes tumor growth in vivo and can trigger chemoresistance in CRC potentially by altering the metabolism of the mitochondrial respiratory chain." (PMID 37248468, 2023).
tumor (continued). "The expression of IGF2BP2 is found to be higher in tumor tissues than in normal tissues, and it is strongly correlated with disease-free survival and clinical phenotypes in patients with papillary TC." (PMID 37915103, 2023). "Meanwhile, the tumor weight from the sh-IGF2BP2 group was substantially lower than that from the sh-NC group." (PMID 37936610, 2023). "To further validate these observations, we extended our analysis to cancer-derived MSCs and evaluated the impact of CSF2 and IGF2BP2 knockdown in GC-MSCs on tumor growth." (PMID 37865637, 2023). "In the xenograft tumor model derived from IGF2BP2 knocked-down LSCC cells, IGF2BP2 knockdown inhibited tumor growth." (PMID 37816718, 2023). "Immunohistochemical images showed the expression levels of RBM15, VIRMA, YTHDC2, YTHDF2, METTL14, and IGF2BP2 proteins in tumor tissues." (PMID 36791151, 2023). "Regarding the in vivo effects of IGF2BP2 knockdown, IGF2BP2 knocked-down LSCC cells were used for the establishment of a xenograft tumor model in nude mice." (PMID 37816718, 2023). "We propose that this abnormal upregulation of IGF2BP2 is partially influenced by the posttranscriptional regulation mediated by the tumor suppressor miRNA-98-5p." (PMID 37936610, 2023). "Immunohistochemistry staining of GLI1, METTL3/14, and IGF2BP2 also confirmed that inhibitors against GLI1 or METTL3 decreased protein levels of GLI1, METTL3/14, and IGF2BP2 in tumor samples." (PMID 37149646, 2023). "Our microarray results also showed a significant upregulation of IGF2BP2 protein, a key reader for m6A modification, in tumor-conditioned MSCs." (PMID 37865637, 2023). "Concordantly, expression of IGF2BP2 significantly correlated with tumor growth in PDX models in the late tumor growth phase 46 days after tumor transplantation." (PMID 37248468, 2023). "Analyzing data from the TCGA dataset demonstrated that IGF2BP2 was highly upregulated in HNSCC tumor tissues compared with that in healthy tissues." (PMID 37936610, 2023). "IGF2BP2 was preferentially secreted by exosomes in the LUAD_IGF2BP2 subpopulation, which was absorbed by the En_IGF2BP2 subpopulation in the tumor microenvironment." (PMID 37353784, 2023). "As a N6-methyladenosine reader protein, Insulin-like growth factor 2 mRNA-binding protein 2 (IGF2BP2) is a critical player in tumor progression and metastasis." (PMID 37936610, 2023). "Concordantly, Spearman correlation coefficients of IGF2BP2 expression with PDX tumor growth for the latter drugs was R2 = 0.31, p = 0.02 for oxaliplatin, R2 = 0.30, p = 0.03 for 5-fluorouracil, and R2 = -0.34, p = 0.01 for bevacizumab." (PMID 37248468, 2023). "We can demonstrate here for the first time, that IGF2BP2 indeed correlates with tumor growth and chemoresistance in vivo." (PMID 37248468, 2023). "IGF2BP2 knockdown significantly decreased tumor weight compared with tumors derived from Lv-sh-NC-transduced TU686 cells." (PMID 37816718, 2023). "The human insulin‐like growth factor 2 mRNA binding proteins 2 (IGF2BP2) was found that it can bind RNAs and impact on their transcript target through post‐transcriptional regulation ways in tumor development." (PMID 36510377, 2023). "IGF2BP2 correlates with CRC tumor growth in vivo and promotes chemoresistance by altering mitochondrial respiratory chain metabolism." (PMID 37248468, 2023). "Histopathological examinations further indicated that IGF2BP2 knockdown significantly decreased the levels of Ki67 and IGF2BP2 in tumor tissues compared with tumors derived from Lv-sh-NC-transduced TU686 cells." (PMID 37816718, 2023). "IGF2BP2 had a relatively high mutation rate in HNSCC, and its expression was significantly positively correlated with tumor purity, and significantly negatively correlated with the infiltration level of B cells and CD8+T cells." (PMID 36793593, 2023). "The role of IGF2BP2 as a tumor promoter in the advancement of cancer is supported by the experimental data gathered so far." (PMID 37828232, 2023).